RNU1-154P (RNA, U1 small nuclear 154, pseudogene)
Gene: Small nuclear RNA gene on chromosome 1 (145,431,527 to 145,431,693, reverse strand). Ensembl gene ENSG00000270384.
Homologues: Orthologues: macaque U1 (76% identical), dog U1 (65% identical), guinea pig U1 (62% identical), rabbit U1 (60% identical), dog U1 (59% identical), rabbit U1 (59% identical), dog U1 (58% identical), rabbit U1 (58% identical), dog U1 (57% identical), dog U1 (55% identical), rabbit U1 (53% identical). Paralogues in human: RNU1-129P (99% identical), RNU1-114P (83% identical), RNU1-1 (68% identical), RNU1-2 (68% identical), RNU1-27P (68% identical), RNU1-28P (68% identical), RNU1-3 (68% identical), RNU1-4 (68% identical), RNVU1-18 (68% identical), RNVU1-29 (68% identical), U1 (68% identical), RNVU1-28 (67% identical), and 133 more.